INS (insulin)
Diseases named in the same sentence as INS in open-access papers (continued):
Sharing a sentence is not in itself a finding about the gene and the disease.
Hypoglycemia (continued). "Regarding the T1DM pathology underlying the pronounced cholinergic neuronal dysfunction, one of the most plausible explanations is the dark side of insulin—hypoglycemia." (PMID 41023469, 2025). "This table presents findings related to the physical health benefits and quality of life impact of using open-source automated insulin delivery systems, such as improvements in glycemic control, time in range, and reduced hypoglycemia." (PMID 39761553, 2025). "Within approximately 6 hours post-administration, a transient phase of pronounced hypoglycemia occurs, distinguished by elevated circulating insulin levels." (PMID 40989847, 2025). "Rapid-acting insulin analogues are effective in limiting postprandial glucose spikes, reducing the 2-h postprandial plasma glucose concentration, and the late hypoglycemia compared to RHI." (PMID 40574081, 2025). "A critical sample obtained during hypoglycemia indicated suppressed insulin (<0.20 μIU/mL) and C-peptide (0.12 ng/mL) levels, thereby effectively excluding insulinoma and factitious hypoglycemia." (PMID 41333493, 2025). "Probably because of the reduced sympathetic response, blood glucose levels 120 and 180 min after insulin injection in Gdf15-KO mice were significantly lower than those in control mice, suggesting an impaired response to hypoglycemia." (PMID 41034527, 2025). "Hyperkalemia in this setting complicates therapy, as insulin is both a treatment for hyperkalemia and a precipitant of hypoglycemia." (PMID 41146800, 2025). "We investigated the response of glucagon and other counterregulatory hormones, insulin and C-peptide concentration, hypoglycemic symptoms, and cognitive function during clamp-induced hypoglycemia in people with T2D treated with tirzepatide versus placebo." (PMID 40964167, 2025). "When introducing a GLP-1 RA with insulin or a sulfonylurea, consider dose reductions to mitigate hypoglycaemia." (PMID 41299307, 2025). "Although sulfonylureas such as glibenclamide are typically used outside pregnancy and considered relatively safe during early gestation, concerns about placental transfer and fetal hypoglycemia in later trimesters led us to switch all patients to insulin." (PMID 41409604, 2025). "We incorporated weight-based insulin dosing formulas and hazard ratios for severe hypoglycemia, cardiovascular and renal outcomes, side effects of new therapies, and mortality." (PMID 40245017, 2025). "This disease is characterized by the overproduction of IGF-2 or its high-molecular-weight precursor, "big IGF-2," which emulates insulin activity, resulting in hypoglycemia." (PMID 41333493, 2025). "Complications such as cerebral oedema, hypoglycemia and hypokalemia are common monitoring targets in both fluid- and insulin infusion- focused studies." (PMID 40407548, 2025). "The incidence of hypoglycemia was 18% in the insulin therapy group, compared to 7% in the oral agents group (p-value = 0.02)." (PMID 40959330, 2025). "In the case of the identification of insulin-mediated hypoglycemia, the evaluation of pancreatic neuroendocrine tumors, which represent the most common and worrisome causes of non-diabetic insulin-mediated hypoglycemia, must be considered." (PMID 39941267, 2025). "Insulinomas are rare pancreatic tumors that present with symptoms of hypoglycemia secondary to unregulated high levels of insulin." (PMID 40322350, 2025). "Many studies and clinical consensus acknowledge the complications of insulin infusions, particularly hypoglycemia and hypoka lemia." (PMID 40407548, 2025). "About half a century ago, Brownlee and Cerami proposed the concept of a glucose-responsive insulin to help mitigate the insulin-induced hypoglycaemia." (PMID 41155876, 2025). "Counterregulatory hormones (glucagon, adrenaline [epinephrine], noradrenaline [norepinephrine], cortisol, and growth hormone) increased during hypoglycemia induction with both insulin treatments at both doses." (PMID 39810242, 2025).
Hypoglycemia (continued). "Patient “2” had a seizure secondary to hypoglycemia during use of the TCIQ system due to self-administrated insulin doses in addition to auto corrections given by the pump." (PMID 38629871, 2025). "All individuals using insulin should be educated on proper administration techniques, hypoglycemia awareness, and glucose self-monitoring." (PMID 40507585, 2025). "This becomes a particularly significant issue concerning the prevention of hypoglycemia during insulin treatment for gestational-IGT." (PMID 39446494, 2025). "The hypoglycemia screen in the neonatal period showed an inappropriate insulin level at the time of hypoglycemia, thus confirming CHI, and genetic analysis showed a homozygous KCNJ11 pathogenic variant." (PMID 40492016, 2025). "In contrast, PRIMO-FRL dynamically adjusts insulin dosing through real-time learning and explicitly incorporates clinical goals—including hypoglycemia avoidance, glycemic stability, and insulin efficiency—into its optimization framework." (PMID 40614090, 2025). "Optimize multiple clinical goals: traditional models focus primarily on TIR, but optimal glycemic control requires simultaneously addressing insulin efficiency, hypoglycemia prevention, and glucose stability." (PMID 40614090, 2025). "This case highlights the importance of patients on an insulin regimen to frequently monitor their glucose levels to prevent hypoglycemia." (PMID 40726866, 2025). "Insulin levels were within normal limits, except in the +1 D period when insulin levels were 2.5 mmol/L (indicating hypoglycemia)." (PMID 40443978, 2025). "Continuous glucose monitoring and automated insulin delivery systems have enhanced the quality of life and glycemic outcomes while reducing severe hypoglycemia and diabetes ketoacidosis hospitalizations." (PMID 40434817, 2025). "An estimated 1.8% of patients receiving any form of insulin therapy develop severe hypoglycemia at least once annually." (PMID 40726866, 2025). "A national survey of DKA management demonstrated a high burden of hypoglycaemia and hypokalaemia episodes, with the use of insulin recognised as the primary driver for these biochemical abnormalities." (PMID 39928758, 2025). "Diazoxide (50–300 mg/d with a maximum dose of 600 mg/d) is commonly used, suppressing insulin secretion and enhancing glycogenolysis, often combined with small, frequent meals to prevent hypoglycemia." (PMID 39740410, 2025). "Studies evaluating the two-bag IV fluid method in adult patients with DKA have demonstrated a shorter time to anion gap closure and resolution of acidemia, decreased duration of insulin infusion, and lower incidence of hypoglycemia." (PMID 41458864, 2025). "Most of the DM patients were taking premixed insulin, with costs lower compared to the longer-acting analogs but have a higher incidence of hypoglycemia compared to the latter." (PMID 39854487, 2025). "These follow-ups included a thorough clinical evaluation, fasting blood glucose levels, and serum insulin assessments to detect hypoglycemia or recurrence." (PMID 39740410, 2025). "Analysis of counterregulatory hormone responses, and responses of insulin and C-peptide during induced hypoglycemia." (PMID 40964167, 2025). "The occurrence of hypoglycemia was a common concern in these studies, which aligns with the clinical need to carefully adjust insulin doses when initiating GLP-1RAs." (PMID 40707821, 2025). "Both assessing the ability of PWDI to self‐manage during inter‐current illness and putting in place practical arrangements to ensure insulin, monitoring equipment, and hypoglycaemia treatments were accessible were seen as key obstacles." (PMID 40324886, 2025). "The existing studies involving bicarbonate administration observe the duration of insulin infusion, length of stay, hypoglycemia rates, hypokalemia rates and common biochemical endpoints, including serum lactate, pH, ketones and serum bicarbonate." (PMID 40407548, 2025).
Hypoglycemia (continued). "Because glutamine is made available by the skeletal muscles during starving periods for gluconeogenesis, it makes sense physiologically that ß-cell GDH prevents glutamine-induced insulin secretion to avoid hypoglycemia." (PMID 40902975, 2025). "Even among cognitively impaired patients, insulin pumps reduced glycemic variability and hypoglycemia when supported by trained caregivers." (PMID 41473654, 2025). "They postulated that altered beta cell sensitivity to changes in circulating levels of glucose leading to inappropriately high insulin secretion was responsible for the severity of hypoglycemia in RYGB." (PMID 39981480, 2025). "Studies indicate that pramlintide can counteract insulin-induced hypoglycemia and regulate hyperglycemic peaks by mimicking amylin’s physiological effects." (PMID 39859479, 2025). "For instance, during hypoglycemia, the brain enhances sympathetic nervous activity to suppress insulin secretion, restoring blood glucose levels to normal." (PMID 41190649, 2025). "FVB/N mice also showed relative hepatic insulin resistance and the highest counter-regulatory response to hypoglycemia." (PMID 39587363, 2025). "The peaks in serum glibenclamide resulting from oral administration stimulate insulin release, resulting in hypoglycemia." (PMID 40722270, 2025). "In the perioperative period, careful attention should be given to appropriate insulin administration, as well as the management of hypoglycemia and hypertension following anesthesia and surgery." (PMID 40585912, 2025). "Other outcomes (e.g., SMPG, hypoglycaemia and insulin dose) were participant‐reported, and body weight was likely investigator‐measured." (PMID 40176458, 2025). "High C-peptide, insulin, and proinsulin at the time of hypoglycemia were consistent with endogenous hyperinsulinemic hypoglycemia." (PMID 40083398, 2025). "Inhibition of PI3K signaling can reduce insulin signaling (despite increases in the serum insulin concentration), thereby improving blood glucose levels and mitigating hypoglycemia." (PMID 40492016, 2025). "Despite growing evidence supporting the efficacy and safety of the MiniMedTM 780G recommended settings (Glucose Target 100 mg/dL and Active Insulin Time 2 hours), their adoption in routine practice remains limited, mainly due to concerns about hypoglycemia." (PMID 41019322, 2025). "The INSULINFARCT trial found a significantly higher rate of hypoglycemia in the intensive insulin therapy (IIT) group—5.7% (<54 mg/dL) and 34.5% (<64 mg/dL)—compared to controls." (PMID 40868089, 2025). "While transient hypoglycemia at 20 min corresponded to reduced Fos levels, consistent with insulin dose‐dependent regulation and glycemic status." (PMID 41024433, 2025). "Hypoglycemia incidence can reach 70% in the postoperative period, necessitating accurate insulin titration and continuous glucose monitoring." (PMID 40707821, 2025). "Infusion of Ex-9 corrected hypoglycemia in all patients with HGB & the reduction in postprandial insulin secretion by Ex-9 was greater in the H-GB group than in the other groups (p<0.05)." (PMID 39981480, 2025). "Because of the tendency to hypoglycemia, the total daily dose of insulin was decreased from 22 units to eight units, that is, two units of insulin degludec before dinner and two units of insulin lispro before breakfast, lunch, and dinner." (PMID 40406776, 2025). "In the United States alone, approximately 100,000 individuals are hospitalized annually due to insulin-induced hypoglycemia, and severe hypoglycemic episodes can be fatal." (PMID 40362391, 2025). "Adverse events were more common in the insulin therapy group, particularly with hypoglycemia and weight gain." (PMID 40959330, 2025). "In glucose management using continuous insulin infusion, artificial pancreas systems prevent blood glucose fluctuations and severe hypoglycemia using insulin pumps and continuous glucose monitoring." (PMID 40415035, 2025).
Hypoglycemia (continued). "Administered in microdoses, it can raise glucose levels within minutes and is particularly beneficial when insulin stacking or delayed carbohydrate absorption threatens to induce hypoglycaemia." (PMID 40718205, 2025). "Individuals with IGF-2-mediated hypoglycemia exhibit fasting hypoglycemia marked by diminished endogenous insulin, ketones, growth hormone, and IGF-1 levels." (PMID 41333493, 2025). "For insulin users, close monitoring of glucose levels and prevention of hypoglycemia should be prioritized." (PMID 41351012, 2025). "Four dogs in the DWP16001 group developed asymptomatic hypoglycemia, which was resolved with insulin dose adjustments." (PMID 40796840, 2025). "Congenital hyperinsulinism (CHI) is a disorder of unregulated insulin secretion, leading to severe hypoglycemia in most cases." (PMID 40492016, 2025). "In particular, hypoglycemia, especially in individuals using insulin or insulin secretagogues, is a significant clinical concern and is considered one of the main barriers to achieving glycemic targets." (PMID 40361775, 2025). "We included original studies that evaluated the comparative effectiveness of different intravenous fluid regimens and insulin protocols in the acute management of DKA or hypoglycemia." (PMID 41262789, 2025). "In the hypoglycemia model, insulin injection significantly reduced blood glucose levels in the NH and NH-V groups, showing typical symptoms of hypoglycemia." (PMID 40589985, 2025). "Bedtime blood glucose is an important safety parameter to avoid nighttime hypoglycemia in insulin-treated patients." (PMID 39939862, 2025). "Insulin can lead to hypoglycemia in diabetic patients, especially when their blood sugars are not monitored when they are out of the hospital." (PMID 40760593, 2025). "Our study identified increased insulin sensitivity as the major driver of juvenile hypoglycemia in GHR-KO pigs." (PMID 41125144, 2025). "Glucose sensors located in the hepatic portal vein and hypothalamic neurons also play a role in insulin secretion in response to food intake and hypoglycemia." (PMID 40940782, 2025). "The idea inspired many designs intending to prevent hypoglycaemia by adjusting the release of exogenous insulin release in response to blood glucose concentrations." (PMID 41155876, 2025). "We report the case of a patient with a metastatic glucagon-secreting pNET who, after 14 years of disease and multiple treatment lines, developed insulin hypersecretion and severe, treatment-refractory hypoglycemia." (PMID 41561059, 2025). "This suggests that the initial rise in peripheral and hepatic insulin sensitivity, leading to hypoglycemia, is primarily fueled by heightened glucose disposal, and reduced endogenous glucose production." (PMID 39838305, 2025). "Secondly, excess insulin inhibits alpha cells, reducing glucagon’s response to hypoglycemia, which in turn decreases glucagon secretion and exacerbates blood glucose decline." (PMID 41573194, 2025). "Factitious hypoglycemia, resulting from covert use of insulin or insulin secretagogues, must be considered in hypoglycemia diagnoses." (PMID 39030378, 2025). "There is low to moderate evidence that SGLT2 inhibitors and GLP1 agonists reduce severe hypoglycemia in comparison with sulphonylureas and insulin." (PMID 40574081, 2025). "The findings of this study revealed that patients who had low level of knowledge regarding insulin self-administration were 4.87 times more likely to develop hypoglycemia compared to patients who had good knowledge." (PMID 40110390, 2025). "We also employed a sexually inexperienced male rat model to study the activation (Fos−positivity) of nesfatin−1 cells in response to female pheromones, as well as the impact of insulin-induced hypoglycemia on this process." (PMID 39859453, 2025).
Hypoglycemia (continued). "In the event of hypoglycemia, before starting glucose infusion a blood sample should be promptly collected in order to measure plasma insulin, cortisol, GH, lactic acid, ammonia, beta-hydroxybutyrate, free fatty acids and urinary ketones." (PMID 40771275, 2025). "This adjustment led to episodes of hypoglycemia, prompting the discontinuation of bolos insulin and a transition to insulin glargine (24 IU sc at 9 pm)." (PMID 41020216, 2025). "This detailed description offers practical insights into the challenges of balancing insulin administration with the prevention of hypoglycemia and hypokalemia in patients with euDKA." (PMID 40941597, 2025). "It is characterized by excessive insulin secretion, leading to recurrent hypoglycemia, often diagnosed through Whipple's triad: hypoglycemic symptoms, documented low plasma glucose, and symptom resolution after glucose administration." (PMID 40124204, 2025). "At that time, laboratory evaluation showed that both C-peptide and insulin levels were suppressed (C-peptide: 0.05 ng/mL; insulin: <0.3 μIU/mL), indicating a physiologically appropriate response to hypoglycemia." (PMID 40677481, 2025). "Studying the glucose behavior, the hypoglycemia compensation mechanisms, and the insulin resistance during DF." (PMID 40585323, 2025). "Our patient had hypoglycaemia (2.25 mmol/L), suppressed insulin (< 1.2 pmol/L), low C‐peptide (0.040 mcg/L), and reduced IGF‐I (5.51 mcg/L), with a positive glucagon stimulation test—all consistent with NICTH." (PMID 40697895, 2025). "Once weekly insulin icodec also fits into the administration frequency of once-weekly incretin analogues, and this combination would be effective from a weight, hypoglycemia, and cardiovascular benefit perspective." (PMID 40156735, 2025). "Accurate monitoring of blood glucose is critical, especially for people who require frequent insulin adjustments to maintain stable blood glucose levels and prevent hypoglycemia." (PMID 39986264, 2025). "Due to beta-cell destruction, there is usually a brief spike in insulin release after STZ treatment, which causes hypoglycemia." (PMID 41309777, 2025). "We present a case of a patient with a stage IV glucagon-producing pNET that, after 14 years and different treatment modalities, presented with new onset insulin secretion and refractory hypoglycemia." (PMID 41561059, 2025). "The iDegLira showed similar HbA1c reduction to basal-bolus therapy but with significantly less hypoglycemia and weight gain, and comparable or superior results compared to monotherapy with insulin degludec or liraglutide." (PMID 41268167, 2025). "Sulfonylureas accounted for more than 30% of hypoglycemic episodes, more frequently than insulin-induced hypoglycemia, especially in the early morning hours." (PMID 39939862, 2025). "CGM provides real-time glucose monitoring during HD, allowing timely interventions such as dietary supplementation, insulin titration, or adjustment of dialysis prescriptions to counteract hypoglycemia." (PMID 41293049, 2025). "In LQT1 and LQT2, genotype-specific alterations in insulin and counter-regulatory hormone secretion contribute to postprandial hypoglycemia." (PMID 40992506, 2025). "The measurement of C-peptide and insulin at the time of hypoglycaemia can already make an important differentiation, for example, for the diagnosis of insulinoma." (PMID 39931615, 2025). "Because insulin levels decrease slowly after this peak, there is a greater chance of late hypoglycemia." (PMID 40137145, 2025). "This is of clinical benefit given the potentially severe consequences of unrecognized hypoglycemia during insulin therapy." (PMID 40337990, 2025). "Critical hypoglycemia labs drawn at 12 h of life were significant for hypoglycemia (glucose: 27 mg/dL), an inappropriately elevated insulin (11.0 μIU/dL) level, and an inappropriately low cortisol (5.1 μg/dL)." (PMID 40605820, 2025).